LINC00939 (long independently transcribed non-coding RNA 939)
Gene: Long non-coding RNA gene on chromosome 12 (125,943,740 to 125,983,667, reverse strand). Ensembl gene ENSG00000249267.
Diseases named in the same sentence as LINC00939 in open-access papers:
LINC00939 is named in the same sentence as 3 diseases in open-access papers, as found by Europe PMC text mining. Sharing a sentence is not in itself a finding about the gene and the disease. The quoted sentences say what the papers report.
lymphoma (1 paper, 2019). A malignant (clonal) proliferation of B- lymphocytes or T- lymphocytes which involves the lymph nodes, bone marrow and/or extranodal sites. "The RNU5E-8P (3q13.31), MIR4447 (3q13.31), RP11–351J23.2 (6q27), and LINC00939 (12q24.32), have to the best of our knowledge not yet been associated with cancer, though RP11–351J23.2 is located in a candidate tumor suppressor gene locus in lymphomas identified by deletion mapping." (PMID 30926794, 2019).
LINC00939 also shares sentences with these, for which no sentence is quoted: cancer (1 paper); tumor (1).